ENSG00000277831 (novel transcript)
Gene: Long non-coding RNA gene on chromosome 13 (44,369,365 to 44,373,570, reverse strand). Ensembl gene ENSG00000277831.
Gene Ontology:
Biological process: SRP-dependent cotranslational protein targeting to membrane, signal sequence recognition
Cellular component: signal recognition particle, endoplasmic reticulum targeting